CD4 (CD4 molecule)
Diseases named in the same sentence as CD4 in open-access papers (continued):
Sharing a sentence is not in itself a finding about the gene and the disease.
Stroke (continued). "On day 2 circulating CD4 + T-bet + T cells were significantly higher in stroke patients compared to controls, and in ATHS compared to CES and controls." (PMID 36180482, 2022). "For example, CD4+ Tregs protect against ischemic brain injury and promote brain repair after stroke." (PMID 35912857, 2022). "A previous study demonstrated that intestinal T cells traffic to the meninges after stroke in the early stage, our experiments illustrated the migration of intestinal CD4+ T cells and γδ T cells to the region of ischemic brain." (PMID 35663549, 2022). "Considering stroke etiopathogenesis, we observed a higher percentage of CD4 + T-bet + T cells in peripheral blood from ATHS patients than CES patients and controls (p = 0.0352 and p = 0.0062, respectively)." (PMID 36180482, 2022). "CD4 memory T cells were significantly down-regulated in stroke whereas M0 Macrophages were noted as significantly up-regulated." (PMID 35250546, 2022). "Evaluating circulating Th1 percentage in peripheral blood on day 2, we observed a significant higher percentage of CD4 + T-bet + T cells in stroke patients compared to controls (p = 0.0154)." (PMID 36180482, 2022). "Within the stroke brain, CD4+ T cells are the major source of the pro-inflammatory cytokines IL-17 and IFN-y." (PMID 35805099, 2022). "Twenty two immune cell subsets were identified in stroke, where resting CD4 T memory cells were significantly downregulated while M0 macrophages were significantly upregulated." (PMID 35250546, 2022). "Weitbrecht revealed that CD4+ T cells facilitate delayed B cell infiltration into the brain and CD4 depletion attenuates post-stroke cognitive impairment." (PMID 35513682, 2022). "Studies on immune responses following stroke have revealed that CD4+CD25+Foxp3+ regulatory T cells play crucial and complex roles in controlling the inflammatory damage caused by stroke as well as modulating immunosuppression." (PMID 36582228, 2022). "The blood CD4+ Tregs showed a reduction similar to that of CD8+CD122+ T cells early after stroke, followed by gradual recovery." (PMID 35912857, 2022). "We then compared the expression of several chemokine receptors by circulating CD8+ TRLs versus the CD4+ Tregs 3 days after stroke to identify receptors potentially important for early CD8+ TRL infiltration." (PMID 35912857, 2022). "The initial findings showed that CD4 memory T cells were significantly downregulated while M0 Macrophages were upregulated in stroke." (PMID 35250546, 2022). "Among patients with CD4 cell counts of ≥ 200 and < 200 cells/μL, the proportions of those with stroke were 2.0% and 4.0%, respectively." (PMID 34983408, 2022). "In all stroke patients the percentage of circulating CD4 + T-bet + T cells on 7 days from stroke onset was significantly higher than on day 2 and 4, and controls (p = 0.0392, p = 0.0019 and p = 0.0011, respectively)." (PMID 36180482, 2022). "85.3 (25%: 68.3; 75%: 93.3) mm3, P > 0.05), thereby confirming a key role of CD4+ T-cells in the process of infarct growth into the penumbra under occlusion, i.e., ultra-early stroke." (PMID 33602266, 2021). "Our data from a combination of IHC and flow cytometry indicate that following stroke, a population of IgA + PCs develops independently of CD4 + helper T-lymphocytes and MyD88 signaling." (PMID 32956832, 2021). "A low CD4 count, immunosuppression and higher levels of HIV viraemia have been associated with higher risk of myocardial infarction and stroke." (PMID 33995812, 2021). "Another study found an increase in CD4+CD28 null lymphocyte cells in stroke survivors or those who died from ischemic stroke." (PMID 33922467, 2021). "Conversely, an exhausted T cell phenotype characterized by an increased frequency of PD‐1+CD4+ T cells has also been observed in patients 48 h post‐stroke." (PMID 33205448, 2021). "This demonstrates that the delayed infiltration of B-lymphocytes into the infarct following stroke can also occur independently of CD4 T-lymphocyte help." (PMID 32956832, 2021).
Stroke (continued). "To determine which of these mechanisms results in the maturation of B-lymphocytes into IgA + PCs following stroke, we performed stroke surgery on WT, CD4−/−, and MHCII−/− mice." (PMID 32956832, 2021). "It has been confirmed that CD8+ Tcs can be recruited into the brain within 3 h after stroke, while CD4+ T cells can be recruited within 24 h, with this population reaching a peak at 72 h after reperfusion and then gradually declining." (PMID 35140708, 2021). "Adoptive transfer of CD4+ CD25+ Treg cells before MCAO in wild-type mice induced bigger stroke infarct size at day 1 post-MCAO." (PMID 34502395, 2021). "Studies in a mouse model of cortical infarction have shown that GITR, triggering on CD4+ T cells, increases post-stroke inflammation and decreases the number of neural stem/progenitor cells induced by ischemia (iNSPCs)." (PMID 34831273, 2021). "To increase our understanding of the IgA + PC response to stroke, we sought to determine the extent to which it is CD4 T-lymphocyte dependent and discovered that IgA + PCs appear in the infarct independently of CD4 T-lymphocyte help." (PMID 32956832, 2021). "In the photothrombotic stroke model in mice, flow cytometry analysis revealed that CD4+ and CD8+ T cells were significantly increased in the ipsilateral thalamus at 14 days post-stroke; however, no changes were detected in B cells, neutrophils or monocytes." (PMID 34884906, 2021). "In IS, preclinical studies with mice lacking CD84 receptor on platelets or T cells, impairing activation, displayed reduced cerebral CD4+ T-cell infiltration and thrombotic activity following experimental stroke resulting in reduced neurological damage." (PMID 34685473, 2021). "Increased frequencies of CD69+ T cells inversely correlated with stroke severity only in the CD4+ compartment." (PMID 33205448, 2021). "CD4+ T cells also contribute to neurodegeneration following stroke, as antibody-mediated depletion of either CD4+ or CD8+ T lymphocytes decreased infarct size, outlining a role for both subsets." (PMID 33173502, 2020). "Following an episode of stroke, there is increased percentage of alveolar macrophages and neutrophils and reduced amount of CD4+ T cells, CD8+ T cells, B cells, NK cells, and eosinophils in the lungs." (PMID 32477327, 2020). "Since electrocoagulation induces a relatively mild stroke, T cells, CD4+ T helper cells, CD8+ cytotoxic cells, T regulatory cells, and B cells were not altered in comparison to sham-treated samples." (PMID 33329318, 2020). "These T cells were predominantly CD8+, e.g., 65% CD8+ vs. 25% CD4+ T cells for the patient deceased at day 1 post-stroke." (PMID 32719588, 2020). "A preferential increase of CD4+ T cells at day 3 after stroke in db/db mice suggests possible involvement of environmental cues in diabetic brain that elicit an early CD4+ T cell response." (PMID 31681285, 2019). "Remarkably, SDI-H mice had increased infarct volumes after ischemic lesions in the MCAO stroke model and exacerbated neurological functional impairment, with increased pro-inflammatory (IL-17+) γδ T cells and reduced (CD4+CD25+) T cells in the spleen." (PMID 31068891, 2019). "Evidence has shown that two distinct peaks of infiltration of CD4+ lymphocytes to the ischemic hemisphere are observed: the first occurring shortly after stroke and the second peaking around day 14 and persisting until day 30 after stroke." (PMID 31133816, 2019). "Previous studies have found that CD4+ Th1 cells secrete pro-inflammatory cytokines, such as interferon gamma, and lymphotoxin alpha in stroke, whereas CD4+ Th2 produce anti-inflammatory cytokines including IL-4, IL-10, and IL-13." (PMID 30572925, 2018). "Fourth, stroke results in increased P-P70S6K and P-S6K protein levels after stroke in WT mice, but CD4 T cell deficit significantly promoted their expression in the KO mice." (PMID 32832192, 2018).
Stroke (continued). "In this study, we investigated the effect of CD4 T cell deficit on oxidative stress responses and the Akt/mTOR pathways in a mouse stroke model with transient MCA suture occlusion by using MHC II gene KO mice with dramatically reduced CD4 T cells." (PMID 32832192, 2018). "Western blot results showed that P-PRAS40 protein levels had no significant changes after stroke, from 5 h to 48 h in WT mice, but CD4 T cell deficits significantly enhanced its levels at 24 h after stroke." (PMID 32832192, 2018). "Inhibition of CD4 T cells reduces stroke-induced infarction by inhibiting neuroinflammation in the ischemic brain in experimental stroke." (PMID 32832192, 2018). "In this study we analyzed the protein levels of soluble CD137 (sCD137) and the expression of CD137 on CD4+ T cells in the peripheral blood of patients with acute atherothrombotic stroke by using the cytometry beads array (CBA) and flow cytometry." (PMID 29697202, 2018). "Alternatively, IP-10, along with other IFNγ-inducible chemokines, promotes post-stroke inflammation via antagonism of the binds to the CCR3 receptor on anti-inflammatory CD4+ T cells." (PMID 30322390, 2018). "Low CD4+ count, prior history of cerebrovascular event, and abdominal obesity were independent predictors of stroke." (PMID 30481210, 2018). "The detrimental effects of CD4 T cells in stroke-induced brain injury have been repeatedly confirmed." (PMID 32832192, 2018). "We and others have reported that CD4 T cells infiltrate into the ischemic brain, suggesting that CD4 T cells are involved in neuroinflammation induced by stroke." (PMID 32832192, 2018). "Some research has revealed that the nadir for frequency of CD3+ and CD4+ cells is on day 0 in stroke patients, suggesting that cellular immunodepression precedes infectious complications in humans." (PMID 27682880, 2017). "We also assessed the percentage of CD4+CD25+ cells in stroke patients, as this has been used previously as a marker for Tregs; however, activated T cells also upregulate CD25 on their cell surface." (PMID 27073295, 2016). "Total Tregs accounted for 5.0% of CD4+ T cells in controls and <2.8% in stroke patients on admission." (PMID 27073295, 2016). "At a ratio of 1 : 2 and 1 : 1 Tregs : PBMCs, the inhibition of CD154 expression on CD4+ effector cells was reduced in stroke patients compared to healthy controls (p < 0.0001)." (PMID 27073295, 2016). "In experimental stroke, CD4+T lymphocytes and CD8+T lymphocytes contribute to inflammation, brain injury, and neurological deficit." (PMID 27554621, 2016). "Our data demonstrate that CD4+CD49−Foxp3+ Tregs are reduced in the peripheral blood of stroke patients." (PMID 27073295, 2016). "On day 3 the Treg-mediated inhibition of CD154 upregulation on CD4+ Teff was impaired in stroke patients." (PMID 27073295, 2016). "Total Tregs, which accounted for 5.0% (median) (range 1.3–10.2%) of CD4+ T cells in healthy controls, were reduced in stroke patients to 2.8% (median) (range 0.03–8.1%) on admission and remained below control values until day 7 (p = 0.0095)." (PMID 27073295, 2016). "Leukocyte subsets in the untreated brain following stroke were predominantly monocytes (~48%), B cells (~31%), activated macrophages (~17%), and smaller populations of neutrophils, CD4+ and CD8 T cells." (PMID 24485041, 2014). "CD80/CD28 interactions played a prominent regulatory role for the CD8+ T-cells and the PD-1/PD-L2 interactions were dominant in controlling the CD4+ T-cell responses in WT mice, after stroke." (PMID 25157219, 2014). "It is conceivable that the infiltration of CD4+ cells, which occurred selectively in C57Bl/6 mice following stroke, contributed to a more severe level of brain inflammation than in FVB mice despite a similar infarct volume." (PMID 25477780, 2014). "Tregs are a subset of CD4+ T cells that are reported to play a protective, immunomodulatory role in the brain over several days after stroke, but a detrimental role during more acute conditions." (PMID 25477780, 2014).
Stroke (continued). "For instance, deficiency of either CD4+ or CD8+ T-cells resulted in the reduction in infarct volume and improvement in neurological performance in experimental models of stroke, suggesting detrimental roles of CD4+ and CD8+ T-cells after stroke." (PMID 25232304, 2014). "The PD-L1 expression was significantly increased on the CD8+ T-cells (p ≤ 0.01) with a trend towards increased expression in the CD4+ T-cells, after stroke in WT splenocytes." (PMID 25157219, 2014). "Both CD4 and CD8 T cell subtypes have been previously implicated in the progression of neurovascular injury following stroke and remain downregulated in ischemic hemisphere of RHP-treated mice after stroke." (PMID 24485041, 2014). "Our understanding of FoxP3+CD25+CD4+ Tregs in stroke has advanced considerably, based on the following key findings." (PMID 23983771, 2013). "FoxP3+CD25+CD4+ Tregs are involved in a variety of central nervous system diseases and injuries, including axonal injury, neurodegenerative diseases, and stroke." (PMID 23983771, 2013). "More studies are required to further clarify the distribution of FoxP3+CD25+CD4+ Tregs in the CNS, peripheral blood, and lymphatic organs at different phases following stroke." (PMID 23983771, 2013). "Particularly, studies reported that FoxP3+CD25+CD4+ Tregs are important neuroprotective immunomodulators in stroke, but their contributive effects towards stroke pathophysiology are still controversial." (PMID 23983771, 2013). "Identification of the poststroke temporal and spatial distribution of FoxP3+CD25+CD4+ Tregs has assisted in elucidating their roles in stroke." (PMID 23983771, 2013). "Stroke resulted in a significant reduction in absolute numbers of T cells, CD4+ T cells, CD8+ T cells, Tregs, B cells, and monocytes, either at 48 h or at 72 h, or both." (PMID 23555048, 2013). "In conclusion, both beneficial and detrimental effects of FoxP3+CD25+CD4+ Tregs in stroke have been currently referenced." (PMID 23983771, 2013). "Although many review articles have focused on FoxP3+CD25+CD4+ Tregs, a new review is necessary for appraising recent research advances in FoxP3+CD25+CD4+ Tregs after stroke." (PMID 23983771, 2013). "Specifically, FoxP3+CD25+CD4+ Tregs exert neuroprotective effects in acute experimental stroke models." (PMID 23983771, 2013). "Altogether, the temporal and spatial dynamics of FoxP3+CD25+CD4+ Tregs after stroke are still controversial." (PMID 23983771, 2013). "However, the specific influence of gender on CD4 + Treg cell function and its relationship with stroke prognosis remains poorly understood." (PMID 40948641, 2025). "Supported by the current literature, we hypothesize that PNU will be effective in a mouse stroke model, and PNU employs an additional mechanism that regulates stroke-induced neuroinflammatory CD4 T-cells." (PMID 40012683, 2025). "CD4+ regulatory T cells (Tregs), as a kind of immunomodulatory cells, can interact with multiple immune cells to play roles in alleviating the inflammatory response after stroke and protecting the blood–brain barrier." (PMID 39878387, 2025). "Interaction analysis of the Effect of CD4 + Treg cells on stroke prognosis by gender." (PMID 40948641, 2025). "This study aims to investigate whether patient gender influences the modulatory role of CD4 + Treg cells in stroke prognosis, thereby providing insights into personalized immunotherapeutic strategies for post-stroke recovery." (PMID 40948641, 2025). "In conclusion, our study highlights that the P2X7 receptor may modulate the secretion of IL-17A in CD4+T cells, thereby exacerbating acute and subacute inflammation following stroke." (PMID 40948793, 2025). "CD4+ T cells can influence post-stroke inflammation; Th1 cells produce IFN-γ and other cytokines and promote inflammation, potentially aggravating brain injury, while Th2 cells mediate anti-inflammatory effects through IL-4 and IL-13 secretion, favoring tissue repair." (PMID 39940640, 2025).
Stroke (continued). "The amount of CTLA-4+ on CD4+ T cells tended (p = 0.26) to be highest in the “stroke t3” group." (PMID 41373643, 2025). "Stroke acutely leads to a strong activation (CD25 upregulation) of both CD4+ and CD8+ T cells." (PMID 41373643, 2025). "Moreover, curcumol significantly suppressed the infiltration of CD3+ T cells, specifically, CD4+ Th cells after stroke." (PMID 38914581, 2024). "Hence, this study quantified serum ATG5 level and the CD4+ T-cell subset, aiming to investigate their inner correlation and their linkage with cognition impairment incidence and deterioration in stroke patients." (PMID 38511768, 2024). "Reduction of CD4+ T-cells by anti-CD4 therapy inhibits brain infiltration by B-cells and may attenuate cognitive impairment after stroke." (PMID 38550918, 2024). "Furthermore, a recent hospital-based study in Sierra Leone presented the pattern of stroke in HIV patients with lower CD4 cell counts." (PMID 38902606, 2024). "In addition, naive CD4 T cells (P < 0.05) were lower at 3 h after stroke, eosinophils (P < 0.05) were lower at 5 h, and CD8 T cells (P < 0.05) and resting NK cells (P < 0.05) were lower at 24 h." (PMID 36644582, 2023). "CD4+ cells also play an important role in B‐cell infiltration after stroke." (PMID 37905592, 2023). "In addition, it was reported that an increase in the number of Treg cells and depletion of CD4+ T cells can improve the long-term outcome after stroke." (PMID 37032832, 2023). "Importantly, taking myelin oligodendrocyte glycoprotein (MOG) through the nose triggers Il-10 secretion from CD4+ T cells, which helps reduce stroke-related disability." (PMID 36793730, 2023). "Researches on animal models suggest that increased numbers of infiltrating CD4+ T cells in brain tissue after IS are associated with poor prognosis of stroke, but anti-CD4+ T cells do not improve the severity of infarction." (PMID 36777635, 2023). "Behavioral recovery after experimental stroke was improved in aged mice depleted of CD4+ T-cells." (PMID 34711943, 2022). "It is already well-known that IL-17 levels tend to be higher in subjects with PACNS-associated stroke compared to non-inflammatory stroke, whereas an increased amount of intrathecal CD4+ lymphocytes is associated with ABRA." (PMID 36295606, 2022). "Additionally, the depletion of CD4+ or CD8+ T lymphocytes with monoclonal antibodies also alleviates the progression of brain damage after stroke onset." (PMID 36685518, 2022). "The presumably quelled phenotype of these potentially compensating CD4+ T cells in our treated group could be important for identifying their influence on stroke pathology." (PMID 35624463, 2022). "The role of CD4+Foxp3+ Treg cells in stroke recovery, however, remains divergent in might be dependent on the stroke model, different microenvironments in the post-ischemic brain as well as the time intervals after the insult." (PMID 35401118, 2022). "Delayed CD4 T cell depletion strongly reduced B cell infiltration at 14 days post-stroke." (PMID 36446955, 2022). "For HAART-naive people living with HIV (PLWH), stroke occurred in various age groups, and early screening for stroke, timely intervention for risk factors among patients in various age groups, and controlling the CD4 count are extremely important in reducing the burden of stroke." (PMID 34983408, 2022). "Following the discovery that CD4+ or CD8+-deficient mice show improved outcome as early as 24 h after reperfusion, numerous studies have shown the deleterious role of T-lymphocytes in experimental stroke." (PMID 35910379, 2022). "In addition, we further performed immunofluorescence staining to evaluate the invasion of CD8+ T lymphocytes or CD4+ T lymphocytes in the ischemic brain 7 days after stroke onset." (PMID 35799259, 2022). "For patients with CD4 counts of < 200 cells/μL, HAART should be initiated as soon as possible to inhibit viral replication and improve immune status to reduce the risk of occurrence of stroke." (PMID 34983408, 2022).